OAT (ornithine aminotransferase)
Diseases named in the same sentence as OAT in open-access papers (continued):
Sharing a sentence is not in itself a finding about the gene and the disease.
prostate carcinoma (1 paper, 2025). A carcinoma that arises from epithelial cells of the prostate gland. "Notably, enzymes governing polyamine biosynthesis, including glutamic oxaloacetic transaminase 2 (GOT2), aminoacylase-1 (ACY1), ODC, and SDS, exhibit overexpression in prostate cancer, while ornithine aminotransferase (OAT) demonstrates insufficient expression." (PMID 41179661, 2025).
prostate tumors (1 paper, 2021). "CDC27-OAT intrachromosomal fusion between CDC27 as a cell cycle regulator and OAT (ornithine aminotransferase, an enzyme which produces ornithine) in aggressive prostate tumors was identified in some patients." (PMID 33750395, 2021).
renal fibrosis (1 paper, 2023). A final common manifestation of a wide variety of chronic kidney diseases characterized by glomerulosclerosis and tubulointerstitial fibrosis. "This demonstrates that asperulosidic acid can up-regulate OAT protein expressions via increasing HNF1α to accelerate the excretion of IS and then alleviates the progression of renal fibrosis." (PMID 38067420, 2023).
schizophrenia (1 paper, 2009). A major psychotic disorder characterized by abnormalities in the perception or expression of reality. "Previous research has implicated metabolic and mitochondrial genes, including ornithine aminotransferase (OAT) and metabolic enzyme cytosolic malate dehydrogenase (MDH1) in schizophrenia, which have not been shown to be influenced by cigarette smoking or antipsychotic treatment." (PMID 19772658, 2009).
small cell lung carcinoma (1 paper, 2021). Small cell lung cancer (SCLC) is a highly aggressive malignant neoplasm, accounting for 10-15% of lung cancer cases, characterized byrapid growth, and early metastasis. "In addition, OAT was found upregulated, 1.3-fold, in small cell lung cancer cell line (NCI-H446) compared to the non-cancerous human bronchial epithelial cell line (16-HBE)." (PMID 33499132, 2021).
tumor (17 papers, 2007 to 2025). "In this study, we identified the overexpression of OAT gene in clinical OV tissues and in-vitro tumor cells, which is significantly positively correlated with MS score." (PMID 40694220, 2025). "PDAC can synthesize ornithine from glutamine and support polyamine synthesis through ornithine aminotransferase (OAT), thereby promoting tumour growth." (PMID 39090116, 2024). "The ability of OAT inhibitors to limit HCC growth makes OAT a potential therapeutic target for inhibiting the growth of this tumor." (PMID 34063343, 2021). "OAT protein expression was significantly higher in NSCLC tissues than that in adjacent non-tumor lung tissues." (PMID 22989455, 2012). "Our prior results showed that transcript levels for the ODC1 gene (encoding the ODC enzyme for polyamine biosynthesis) was significantly upregulated in tumor tissues compared to controls whereas the transcript levels of OTC and OAT were downregulated in tumor tissue." (PMID 30235319, 2018). "This process is mediated by ornithine aminotransferase (OAT) and supports polyamine synthesis essential for tumor growth." (PMID 40630951, 2025). "OAT, AGMAT, and SMS are only up-regulated in tumor tissue (Fig. 3a9, a12, a17, b6, b8, and b10), while ODC1 and SRM are highly expressed in tumor and lymphoid tissues (Fig. 3a13, a15, b7, and b9)." (PMID 37164975, 2023). "OAT protein expression was determined in 55 cases of NSCLC and 17 cases of adjacent non-tumor lung tissues by immunohistochemical staining." (PMID 22989455, 2012). "In the light of this evidence, we observed different cellular localization of OAT, LTC4S and TPD52 in PCa cells procured from AA and CA, which may imply a possible role in tumor aggressiveness in AA but it needs further studies." (PMID 30397274, 2018). "Here, we did see the inhibitory effect of OAT knockdown on tumor cell growth, but it is not comparable to that with blockade of PB." (PMID 26598224, 2015). "Moreover, we were able to validate the expression of 16/57 differentially expressed proteins in MDCKYBX1 tumour xenografts, some of which were mitochondrial (ACADSB, SLC25A1, IARS2, and OAT)." (PMID 25980435, 2015). "A significant difference of OAT protein expression was existed between squamous cell lung cancer and adenocarcinoma (P < 0.05), but was not correlated with the gender, age, lymph node metastasis, tumor size, and TNM stages." (PMID 22989455, 2012). "Interestingly, OAT's expression pattern in our tumor samples does not suggest AR-mediated stimulation, but rather repression, possibly reflecting interactions of AR signaling with input from other cell types or components of the extracellular matrix, which only occur in vivo." (PMID 17553165, 2007).
cancer (16 papers, 2012 to 2026). A tumor composed of atypical neoplastic, often pleomorphic cells that invade other tissues. "Another important difference to the Huh7.5 cancer line is the more efficient transcription of the OAT gene that links ornithine and urea cycles with the proline metabolic pathway." (PMID 37189460, 2023). "Third, bioinformatics analysis of the OAT gene sequence predicts the existence of binding sites for several transcription factors involved in cell cycle or cancer genesis, such as EVI-1 (two sites)." (PMID 28272331, 2017). "Besides helping us to understand the mechanisms of action of OAT and its involvement in metabolism, recent advances on the role of OAT in cancer and in other pathological processes (see last part of this paper) have fueled interest in OAT inhibitors." (PMID 28272331, 2017). "It has been proven that ornithine aminotransferase (OAT) might play an important role in the oncogenesis and progression of numerous malignant tumors." (PMID 22989455, 2012). "OAT inhibition could thus be beneficial in treating HCC or other cancers." (PMID 28272331, 2017). "There is increased expression of key metabolic enzymes (Arg1, OAT and PYCR1) in fibrotic tissue and cancer." (PMID 37752116, 2023). "Ornithine is synthesized in cancer cells by arginase 2 (ARG2) during S/G2/M phases only, and by the ornithine aminotransferase (OAT) in normal cells." (PMID 37108109, 2023). "Orn acts both as a substrate of ornithine decarboxylase (ODC) to produce polyamines and as a substrate of ornithine aminotransferase (OAT) to produce Pro, and all these products are involved in the promotion of cancer progression." (PMID 36030300, 2022). "Cancer cells exclusively use arginase 2 (ARG2) to synthesize ornithine, whereas normal epithelial cells depend on ornithine aminotransferase (OAT)." (PMID 32296576, 2020). "Combined with our data, these results suggest that OAT may play an important role in the metabolism of rapidly proliferating cells, such as fibroblasts in patients with IPF, as well as in some cancers." (PMID 38413821, 2024). "First, inhibition by diazonamide A, a natural toxin with anti-mitotic properties, was shown to act through OAT in cancer cell lines, but without inhibiting its activity." (PMID 28272331, 2017). "Metastatic MDA-MB-231 cell line-derived MVs exhibiting higher enzymatic activity of OAT than MVs of the non-cancerous MCF10A cell line suggest that cancer-derived MVs may contribute to the overall metabolic status and consequently increase vulnerability in BC." (PMID 33499132, 2021).
infection (5 papers, 2014 to 2025). The state of being infected such as from the introduction of a foreign agent such as serum, vaccine, antigenic substance or organism. "As for ornithine aminotransferase (DELTA-OAT), whose expression is increased by CqMV1 infection, it has been reported to enhance tolerance to multiple abiotic stress." (PMID 35053093, 2022). "Compared with the H1N1pdm09 infection, the down-regulation of OAT in H7N9-infected A549 cells at 24, 48 and 72hpi maybe block cell division and cause cell death." (PMID 27223893, 2016). "In 3 independent western blot analyses (P<0.05), as shown in, compared with the H1N1pdm09 infection, the down- or up-regulated proteins of CAPZA1 (33KDa), OAT (49KDa), PCBP1 (37KDa), EIF5A (18KDa), PAFAH1B2 (26KDa) in H7N9 infection were consistent with the 2-D DIGE results." (PMID 27223893, 2016).
metabolic disease (4 papers, 2018 to 2023). A congenital disorder (due to inherited enzyme abnormality) or acquired (due to failure of a metabolically important organ) disorder resulting from an abnormal metabolic process. "It is a metabolic disorder due to mutations on the gene encoding vitamin B6 dependent enzyme ornithine aminotransferase (OAT), in which resulted 10 to 20-fold increased level of plasma ornithine." (PMID 33602140, 2021).
genetic disease (2 papers, 2021). "As a rare genetic disorder caused by OAT gene mutations, GA is particularly prevalent in Finland with unknown reasons and it also has been reported in many other countries around the world." (PMID 33602140, 2021).
OAT also shares sentences with these, for which no sentence is quoted: chorioretinal degeneration (3 papers); Atrophy (2); gastric cancer (2); steatosis (2); acute leukemia (1); Alzheimer disease (1); bipolar disorder (1); brain tumours (1); cardiovascular disorder (1); Cerebral ischemia (1); chronic lung disease (1); Cognitive impairment (1); diabetes (1); glaucoma (1); glioma (1); Hepatic fibrosis (1); Infertility (1); Insulin resistance (1); liver cancer (1); metastatic carcinoma (1); ornithinemia (1); Parkinson disease (1); retinal disease (1); Retinal dystrophy (1); retinitis (1); type 2 diabetes (1).